MDM2 (MDM2 proto-oncogene)
Diseases named in the same sentence as MDM2 in open-access papers (continued):
Sharing a sentence is not in itself a finding about the gene and the disease.
lymphoma (continued). "Our results provide confidence towards the development of MDM2 inhibitors for lymphoma patients in the clinic." (PMID 19958544, 2009). "The molecular docking and MMGBSA analysis of the compound DMBP against a panel of lymphoma-associated protein targets—AKT1, HSP90AA1, MTOR, MAPK1, and MDM2—revealed distinct binding affinities and interaction profiles, indicative of its potential as a multi-target therapeutic agent." (PMID 40699833, 2025). "Combining FPFT-2216 with an MDM2 inhibitor exhibited synergistic antiproliferative activity and induced rapid tumor regression in immunodeficient mice subcutaneously transplanted with a human lymphoma cell line." (PMID 38265263, 2024). "Further experiments are required to decipher the role of MDM2 in these lymphoma types." (PMID 37568720, 2023). "Interestingly, the observation that inhibition of MDM2 in EμEBNA1 transgenic lymphoma cells led to reduced EBNA1 expression alongside that of E2F1, suggests a further link between EBNA1 and E2F1." (PMID 29642420, 2018). "The first-in-class MDM2 degrader KT-253 (NCT05775406) is under clinical evaluation for high-grade myeloid malignancies, solid tumors, and lymphomas." (PMID 40866949, 2025). "DS3032b, a MDM2 inhibitor, was evaluated in a phase I study of patients with WDLPS/DDLPS, solid tumors, and lymphomas." (PMID 37888062, 2023). "Critically, unlike traditional MDM2 inhibitors, KT-253 shows no neutropenia or thrombocytopenia in advanced lymphoma/ALL patients, addressing a major toxicity limitation of occupancy-driven inhibitors." (PMID 40866949, 2025). "Finally, phase I trials investigating the MDM2 inhibitors CGM097 and DS3032b have been studied in solid tumors and lymphoma." (PMID 36439412, 2022). "Several isoforms of MDM2 are expressed in BL cell lines (both EBV positive and negative), additionally high levels of MDM2, along with high levels of c-Myc and E2F1 are consistently detected in EμEBNA1 transgenic mouse lymphomas." (PMID 29642420, 2018).
lymphoma (continued). "Furthermore, data from early phase clinical trials have demonstrated encouraging anti-tumor activities of MDM2 and XPO1 inhibitors in lymphoma patients." (PMID 27626308, 2016). "With the recent indication that MDM2 plays a role in EBNA1-mediated tumorigenesis and that inhibition of MDM2 in EμEBNA1 transgenic lymphoma cells leads to reduced EBNA1 expression alongside that of E2F1, it is interesting to speculate about the role of MDM2 in this process." (PMID 29642420, 2018). "An independent cohort of 51 DLBCL cases with (n = 31) and without (n = 20) lymphomatous effusions were immunohistochemically studied to validate the role of MUM4, HDAC1 and MDM2 overexpression in the formation of lymphomatous effusions." (PMID 34635181, 2021).
bladder cancer (52 papers, 1995 to 2025). "For instance, a single A > G intronic mutation in MDM2 from bladder cancer introduces a new 118-bp exon before the last canonical exon." (PMID 33149122, 2020). "Of these, NQO1, CCL2, and MDM2 are associated with increased risk or tumor promoting function in bladder cancer." (PMID 28122346, 2017). "The labels mean the genes VEGFA, MMP2 and MDM2 from the target gene set of the cancers (C) associated co-function module can be mapped to the Bladder cancer pathway." (PMID 28340554, 2017). "Additionally, MDM2 had been identified as a marker linked with the anti-tumor immune response, offering prognostic insights for bladder cancer." (PMID 38961326, 2024). "The SNP309 polymorphisms of MDM2 is associated with an improved survival rate of bladder cancer." (PMID 37497216, 2023). "Moreover, we investigated the underlying mechanism of SNHG1 in the bladder cancer process via miR-9-3p/MDM2/PPARγ axis." (PMID 36230661, 2022). "The overexpression of MDM2 has been reported to counteract the inhibitory effects of miR-379–5p on the proliferation, migration, and invasive capabilities of bladder cancer cells." (PMID 40771930, 2025). "In agreement with prior literature, significant copy number alterations involved deletion of CDKN2A/B, leading to cell cycle dysregulation, and focal amplifications in CCND1 and MDM2, which are well-documented events in bladder cancer." (PMID 41373802, 2025). "MDM2 is generally considered to be an oncogene, and different types of tumors, including breast, pancreatic, and bladder cancers, exhibit MDM2 amplification." (PMID 39273281, 2024). "For example, MDM2 SNP309 G-variant was revealed to be correlated with tumor cell invasive growth and the risk of bladder cancer." (PMID 37215134, 2023). "AURKB (Aurora kinase B) was increased after MDM2 upregulation induced by lncRNA PVT1 in bladder cancer cells." (PMID 37215134, 2023). "MDM2 targeted PPARγ for ubiquitination and degradation, leading to facilitating the development of bladder cancer." (PMID 37215134, 2023). "For example, miR-143 inhibited the expression of MDM2 and performed a tumor suppressive function via inhibition of cell growth and migration in bladder cancer." (PMID 37215134, 2023). "LncRNA SNHG1 sponged miR-9-3p expression and upregulated the expression of MDM2 in bladder cancer cells." (PMID 37215134, 2023). "In summary, silencing SNHG1 decreased the tumorigenesis of bladder cancer cells in vivo by decreasing MDM2 expression through miR-9-3p." (PMID 36230661, 2022). "Collectively, this study provides evidence that SNHG1 upregulation promoted cell proliferation but depressed cell apoptosis in bladder cancer via MDM2-inhibited PPARγ by binding to miR-9-3p." (PMID 36230661, 2022).
bladder cancer (continued). "Nevertheless, previous studies detected that MDM2 was highly expressed as a proto-oncogene in bladder cancer." (PMID 36230661, 2022). "POU5F1 can enhance tumour immune response by upregulating the TET1-dependent NRF2/MDM2 axis in bladder cancer." (PMID 36685927, 2022). "Accordingly, PPARγ activation gave rise to inhibition of proliferation of 9 bladder cancer cell lines All in all, the SNHG1/miR-9-3p/MDM2/PPARγ axis was involved in bladder cancer progression." (PMID 36230661, 2022). "A recent study reported a C1797G polymorphism in the protein coding gene of murine double minute 2 (MDM2) promoter of bladder cancer, and that the C to G substitution enhances the affinity of C/EBPα to this region in the MDM2 promoter." (PMID 24648007, 2014). "In particular, in bladder cancer cells, a role for MDM2 in hTR promoter regulation, has been recently demonstrated." (PMID 20920335, 2010). "Additionally, they found that SNHG1 enhances the proliferation of bladder cancer cells through the suppression of apoptosis and promotes MDM2 expression by binding to miR-9-3p, which in turn facilitates the ubiquitination and downregulation of PPARγ." (PMID 40771930, 2025). "Another study reported that lncRNA and MDM2 influence cancer progression through ubiquitination in bladder cancer, particularly investigating the mechanism by which lncRNA plasmacytoma variant translocation 1 (PVT1) regulates adriamycin (ADM) resistance in bladder cancer cells." (PMID 40771930, 2025). "Moreover, downregulation of CA9, NDRG1, SLC2A1, VEGFA, and upregulation of MDM2 were further verified in an additional bladder cancer cell line, 5637 cells." (PMID 38339062, 2024). "Hispolon promoted the ubiquitination and degradation of MDM2 in bladder cancer cells." (PMID 37215134, 2023). "Silencing of USP22 promoted the degradation of MDM2 in bladder cancer cells." (PMID 37215134, 2023). "Similarly, a prior study uncovered that inhibition of MDM2 exerted tumor-suppressive effects on bladder cancer by decreasing cell invasive, proliferative, and migratory capacities." (PMID 36230661, 2022). "Taken these findings into account, we hypothesized that the SNHG1/miR-9-3p/MDM2/PPARγ axis correlated to the progression of bladder cancer." (PMID 36230661, 2022).
bladder cancer (continued). "miR-9-3p may be involved in the progression of bladder cancer by inhibiting the expression of MDM2, which was further verified by experiments." (PMID 36230661, 2022). "Furthermore, MDM2 induced ubiquitination and degradation of PPARγ that contributed to the development of bladder cancer." (PMID 36230661, 2022). "Overexpression of MDM2 could reportedly neutralize the depressive effect of miR-379-5p on bladder cancer cell proliferative, migratory and invasive capacities." (PMID 36230661, 2022). "Hence, hispolon downregulated MDM2 via degradation in bladder cancer." (PMID 37215134, 2023). "Notably, the present study provided evidence that SNHG1 promotes MDM2 expression by binding to miR-9-3p to promote PPARγ ubiquitination and downregulate PPARγ expression, thereby resulting in elevation of bladder cancer cell proliferation in vitro and tumorigenesis in vivo." (PMID 36230661, 2022). "MDM2 is upregulated by the OCT3/4/TET1/NRF2 axis, which contributes to increased immune escape in bladder cancer." (PMID 37497216, 2023). "For instance, there are three edges connecting the genes with the pathway ‘hsa05219: Bladder cancer’ together with the labels of “C N VEGFA”, “C N MMP2” and “C MDM2”." (PMID 28340554, 2017). "Crucial role of hispolon in ubiquitination and downregulation of MDM2 via MDM2-recruited activated ERK1/2 was reported, projecting the phenolic compound as a potential anti-tumor agent in breast and bladder cancers." (PMID 22582152, 2012). "Similarly, abnormal amplifications of the ERBB2, mdm2 and FGFR3 genes were found at a high frequency in bladder cancer." (PMID 38067407, 2023).